ERG (ETS transcription factor ERG)
Diseases named in the same sentence as ERG in open-access papers (continued):
Sharing a sentence is not in itself a finding about the gene and the disease.
tumor (continued). "ets21c encodes the single ortholog of human Friend leukemia insertion 1 (FLI1) and ETS-related gene (ERG) that are commonly overexpressed or translocated in various tumor types." (PMID 26398940, 2015). "We also implemented a quantitative analysis of ERG expression throughout different tumor types using a novel computational methodology via a custom Matlab 2008b program." (PMID 25881913, 2015). "Tumours collected at the end of experiments were analysed for the expression of ERG oncoprotein by Western blot and the results revealed a high reduction of ERG protein levels." (PMID 25933120, 2015). "Interfering with Usp9X function by chemical inhibition through the deubiquitinase inhibitor, WP1130, results in proteasomal degradation of ERG and impaired growth of tumor cells exhibiting this genetic alteration in vivo." (PMID 26008975, 2015). "Results were compared to tumor phenotype, ETS-related gene (ERG) status, and biochemical recurrence." (PMID 25894226, 2015). "Genomic mechanisms of resistance to taxane-based chemotherapy are unclear, although recent data suggest that ERG affects microtubule dynamics and that ERG overexpressing tumours are consequently more resistant to docetaxel." (PMID 25896606, 2015). "We demonstrated the presence of CTCs carrying oncogenic EWS–FLI1/ERG fusions in only 19 % (n = 3) of ES patients with confirmed EWS/FLI1 rearrangements in tumor specimen." (PMID 25008066, 2014). "WP1130 also considerably abrogated tumor angiogenesis in ERG-overexpressing VcaP cells xenograft nude mice." (PMID 24739220, 2014). "As previously shown, ERG expression sometimes varied when comparing different tumor foci from the same patient." (PMID 24505269, 2014). "Expression of ERG in at least one tumor core was significantly positively correlated with advanced tumor stage, high Gleason score and presence of metastasis." (PMID 24505269, 2014). "We also found six tumor related genes, TUSC2, TP53I3, TSSC4, RAB23, RAB39A, and ERG, which function as either tumor suppressor genes or oncogenes." (PMID 24007313, 2013). "In the present case, strong nuclear positivity for ERG immunostaining was observed in the vascular space forming tumor cells, as well as the papillary structure forming cells." (PMID 23607024, 2013). "ERG expression beyond a certain threshold would convey castration resistance to the tumor cells, which in turn increases the AR copy number and expression to compensate for androgen deprivation, contributing to disease progression and metastasis." (PMID 24098661, 2013). "The index tumor in CA men was ERG positive in 31 of 63 patients (49%), which was significantly more common than the 10 of 63 positive (16%) in AA men." (PMID 23892597, 2013). "The advantage of the use of an antibody-based detection method for ERG is that is allows multiplexing for different cell markers that can further characterize tumor cell heterogeneity." (PMID 22558290, 2012). "The major ETS genes involved in rearrangements in ESFT and PCa, FLI1 and ERG, respectively, belong to the same subfamily, have 98% sequence identity in the DNA binding domain, and have been found rearranged in both neoplasias." (PMID 23185447, 2012). "This metastasis originated from the LHSR TMPRSS2/ERG primary tumor, as it stained positive with human-specific anti-AR antibody." (PMID 21747944, 2011). "TMPRSS2–ERG T1/E4 fusion-positive tumours had differentially regulated mRNAs observed in multiple studies, the most significant one coded for ERG." (PMID 20068566, 2010). "In both the Toronto and Swedish cohorts, ERG was uniquely the most significant differentially regulated transcript in TMPRSS2–ERG fusion-positive tumours." (PMID 20068566, 2010). "ERG oncoproteins influence tumor cell proliferation, but exert a more pronounced effect on migration and invasion through broad changes in gene expression." (PMID 20860828, 2010).
tumor (continued). "We observed Nkx3.1 promoter occupancy by ERG also in clinical tumor samples by performing ChIP in ERGhigh and NoETS tumors." (PMID 20479932, 2010). "We constructed a TMA block containing cores from all of the cancers harbouring ETV1 re-arrangements (23 tumours) and six randomly selected cancers with an ERG gene rearrangement." (PMID 18594527, 2008). "On the basis of the Kaplan–Meier survival estimates, the group of patients who had tumours with TMPRSS2:ERG gene fusion had a much greater rate of recurrence at 5 years (58.4%) than patients who lacked the fusion gene (8.1%; P<0.0001)." (PMID 17971772, 2007). "Additionally, ERG+/PTEN− tumours commonly exhibit immunosuppressive characteristics, such as reduced CD8+ T-cell infiltration and enhanced recruitment of myeloid-derived suppressor cells." (PMID 40165885, 2025). "Notably, ERG expression was heterogeneous, with much lower ERG expression in the areas with invasive tumor." (PMID 41321318, 2025). "PCa tumour molecular subtypes based on ERG/PTEN expression across the populations." (PMID 40165885, 2025). "In our set, CD31 and ERG stained virtually 100% of the tumor cells." (PMID 38902365, 2025). "Taken together these findings indicate that AR-targeted therapies may increase PI3K/AKT pathway activity by several mechanisms, with decreased ERG expression in T:E fusion tumors being a major mechanism in this tumor subset." (PMID 41321318, 2025). "Importantly, ERGi-USU significantly inhibited the growth of ERG-positive tumor xenografts in nude mice." (PMID 40427154, 2025). "Additionally, tumor cells often exhibit immunoreactivity for endothelial markers such as ERG, CD31, CD34, and factor VIII-related antigen." (PMID 40895865, 2025). "The interplay between TMPRSS2:ERG fusion (often represented by ERG expression) and PTEN loss allows for the classification of PCa into molecular subtypes providing critical insights into tumour biology." (PMID 40165885, 2025). "Given that IKAROS limits ERG expression, we hypothesized that its tumor suppressor function may involve chromatin-regulatory complexes." (PMID 41509392, 2025). "Moreover, by immunohistochemistry (IHC), the tumor showed diffuse reactivity for vascular markers, including ERG, CD31, CD34, and D2-40, as well as for TFE3, while being negative for MUC4, CAMTA1, smooth-muscle actin, desmin, S100 and keratins." (PMID 40879254, 2025). "Our in vivo results are therefore consistent with the in vitro experiments and suggest that not only do ETV1 and ERG promote the formation of larger tumours, but that MET also participates in these effects, notably observed by the reversal of ETV1/ERG‐induced tumour progression by Capmatinib." (PMID 39374163, 2025). "Notably, IHC for ERG showed that ERG was markedly decreased in the residual tumor in the RP specimens versus the pretreatment biopsies." (PMID 41321318, 2025). "The virtual independency of the adenine requiring proliferative activity of ERG positive tumor cells from MTAP expression levels might suggest that the MTAP dependent salvage pathway for adenine synthesis has reduced importance in these cancers." (PMID 40554389, 2025). "We next asked whether luminal or IM cell state signatures derived from ERG+ GEMMs might distinguish between different clinical outcomes in ERG+ human patients with PCa by interrogating baseline tumor transcriptomes (bulk RNA-seq) in two widely studied cohorts." (PMID 40858905, 2025). "Contributing factors may include genetic predisposition and molecular features such as elevated TMPRSS2:ERG fusions and aggressive tumor biology." (PMID 40792342, 2025). "Furthermore, the study revealed that silencing YAP effectively inhibited the trends of cell growth and tumor transformation induced by ERG overexpression in prostate epithelial cells." (PMID 39963114, 2025).
tumor (continued). "Both CD31 and ERG strongly stain both blood and lymphatic vessel endothelial cells, making the combined application of these antibodies particularly beneficial in confirming the endothelial nature of the tumor." (PMID 38902365, 2025). "We therefore proposed that MET may be a relay in the expression of the ETV1 and ERG genes in hormone‐independent stages, leading to significant tumour capacity." (PMID 39374163, 2025). "FISH performed on PDX tumor material could confirm the presence of the TMPRSS2: ERG rearrangement, reassuring the final diagnosis of PCa metastases." (PMID 38907236, 2024). "Whereas some studies showed its direct association with EMT and poor prognosis, others found that ERG positivity was not linked to either aggressive tumor characteristics or a worse prognosis." (PMID 39118797, 2024). "FISH analysis of tumor tissue from the second SMN revealed the EWSR1/ERG fusion gene." (PMID 39596402, 2024). "Among them, ERG, ZFX and SOX2 have been reported to be highly associated with tumor development." (PMID 38389573, 2024). "However, the intensity of ERG expression is typically weaker than that observed in the endothelium of surrounding vessels (or that observed in EWSR1::SMAD3-rearranged tumor) and comparison with these structures is diagnostically useful." (PMID 39264472, 2024). "ERG or CD31 expression confirms the vascular nature of tumor cells." (PMID 38741104, 2024). "Future studies will also need to investigate if the expression of ETS1 and the other transcription factor genes data suggests some EWS tumor cells express at higher levels than EWS cell lines is a result of heterogenous EWSR1:FLI1/ERG expression and/or due to the transduction of external stimuli." (PMID 38187702, 2023). "But unlike the results of the ERG expression, the association with the tumor grade revealed significant correlations when we compared the MVD in well-differentiated tumors with moderate differentiation in both inside and outside the tumor vascularity." (PMID 38186453, 2023). "Proteomic profiling study of primary PCa revealed that high pro-NPY expression, regardless of the ERG status, was associated with an increased PCa-specific risk of death, especially in patients with Gleason score ≤ 7 tumours." (PMID 36583743, 2023). "Later, it was established that negative ERG tumor status was associated with poorer BCR‐free survival in Caucasian, but no relation was found in African–American patients." (PMID 36329628, 2023). "Another study found that high DAXX expression correlated with transmembrane protease, serine 2 (TMPRSS2)/ERG rearrangement, ERG expression, high tumor Gleason grade, advanced pT stage, high Ki-67 labeling index, and early prostate-specific antigen (PSA) recurrence." (PMID 37958340, 2023). "When tested in an aggressive OSCC xenograft model, TCZ-loaded JNP showed high levels of xenograft inhibition and outperformed all control groups with respect to inhibition of tumor cell proliferation, reduction in tumor size and reduced expression of the proto-oncogene ERG." (PMID 36635487, 2023). "The miR-4482 and miR-3912 can bind to ERG mRNA at definite sequences in 3ʹUTR and may act as potential tumor suppressors." (PMID 37310937, 2023). "We believe that a further study including a higher number of patients is essential to re-evaluate the real impact of the capillaries on patient survival, and of course, an additional investigation is required to explain the background of ERG expression in tumor cells of HGSC." (PMID 37830603, 2023). "Notably, there was no noteworthy disparity in copy number variations (CNV) between ERG+ and ERG- tumor cells." (PMID 37746302, 2023). "Cases with a positive ERG status showed nuclear positivity in more than 90% of tumor cells." (PMID 37894380, 2023). "Furthermore, the tF-1 tumor subtype has more frequent ETS family gene fusions (such as ERG and ETV1) than the tF-2 tumor subtype." (PMID 36661724, 2023).
tumor (continued). "Because a low level of PSAP immunostaining was strongly linked to TMPRSS2:ERG fusion, as detected by IHC and FISH (p < 0.0001 each), associations with tumor phenotype and prognosis were also separately analyzed in cohorts of ERG-negative and positive tumors." (PMID 37892063, 2023). "Androgen-driven ERG-TMPRSS2 gene fusions were associated with disease recurrence and tumor relapse." (PMID 35203446, 2022). "However, given the disparate cytologic and architectural features, we performed ERG IHC and discovered the presence of a lower grade ERG-positive tumor adjacent to a higher grade ERG-negative tumor." (PMID 35050902, 2022). "We surmise that PGC1α mediated coactivation of ERG fusion is largely tumor type and context-dependent and might be advantageous during the transition to castration-resistant phenotype." (PMID 35508713, 2022). "In addition, although the level of the proliferation marker Ki-67 was similar between the 2 groups, there was decreased tumor angiogenesis in treated mice, as indicated by lower ERG-positive staining." (PMID 35471938, 2022). "In addition to its role in regulating tumor cell invasion and proliferation, ERG also plays an important role in negatively regulating tumor cell differentiation by inhibiting the transcription of genes such as KLK3/PSA and SLC45A3/Prostein." (PMID 35563163, 2022). "Among the 22 candidate driver genes found in SV hotspots, previously reported PCa-related gene ERG interruption at hotspot chr21: 38–39 Mbp (37/40 tumours) was biased towards European-derived tumours (21/37), representing 34.4% and 13.0% of tumours from European and African patients, respectively." (PMID 36045381, 2022). "Furthermore, we found inversions with BND interrupting TMPRSS2 and ERG genes in three tumours from European patients and one RNA-seq validated tumour from the African patient UP2103." (PMID 36045381, 2022). "In the primary tumor biopsies, 6 cases contained both ERG+ and ERG− areas." (PMID 36358614, 2022). "To test this hypothesis, we integrated ERG+ tumor cells and ERG- tumor cells separately with LE cells and performed sub-clustering analysis." (PMID 35013146, 2022). "We conclude that ERG is a pivotal mediator in tumor development and is involved in many cellular processes, including cell proliferation, de-differentiation, angiogenesis, and cancer stem cell homeostasis and is implicated in the epithelial to mesenchymal transition pathway." (PMID 35563163, 2022). "Considering the pathological role of the TMPRSS2/ERG fusion gene, this function of Efp could seem to be tumor suppressive." (PMID 35954308, 2022). "We performed a comprehensive pathological review of over 300 RPs from a prospectively collected multi-institutional cohort and mapped and graded each tumor focus based on H&E examination and molecular classifiers (ERG rearrangement, SPINK1 overexpression, PTEN deletion, and SPOP mutation)." (PMID 35050902, 2022). "Therefore, it is possible that the genetic background of the tumor dictates the oncogenic consequences of ERG overexpression." (PMID 36212399, 2022). "The transcriptional differences between ERG+ and ERG− tumor cells suggested that they might give rise to differential responses in the tumor microenvironment." (PMID 35013146, 2022). "Intronic genomic breakpoints originated from the rearrangement of an AR-regulated gene with ERG—and in general from any somatic genomic aberration—represent cancer-specific sequences that could be used to selectively kill ERG-positive tumor cells." (PMID 35267426, 2022). "Similar to the clonogenic growth assay however, the S96E mutation allowed ERG to promote tumor formation in the absence of mAKT." (PMID 34314419, 2021). "It is also unclear which transcriptional targets of ERG are necessary to promote tumor formation." (PMID 34314419, 2021). "In contrast to ERG alone, both ERG S96E and ERG/mAKT can promote tumor formation." (PMID 34314419, 2021).
tumor (continued). "Interestingly, ERG-positive, and PTEN-loss tumours were associated with reduced AR expression, suggesting androgen-independent survival mechanisms in these tumours." (PMID 35008330, 2021). "Notably, TBL1XR1 and ZEB2 mutations were enriched in ERG-deleted ALL (present in 21% and 14% of tumours, respectively)." (PMID 34753926, 2021). "Immunohistochemical markers CD31, CD34 and ERG confirmed the vascular nature of the tumor." (PMID 33593408, 2021). "Similarly, McKay et al29 recently reported an association between residual tumor volume and PTEN aberrations and ERG expression." (PMID 34322653, 2021). "Based on the incompatibility between the two tumor subtypes, our work enabled the development of specific custom signatures related to AR and ERG transcript that are necessary to drive proliferation and tumorigenesis in the context of ERG-positive and SPOP-mutants tumors." (PMID 33531470, 2021). "Interestingly, in line with a relation between miR-424 and tumor aggressiveness, we found increased expression and EVs-mediated release of miR-424 in LNCaPabl cells, ERG/PTEN mice and PDX LuCaP #145.2, models of hormone-refractory or invasive adenocarcinomas." (PMID 33500545, 2021). "They showed that ERG-positive and PTEN-loss tumours harboured greater residual disease." (PMID 35008330, 2021). "Microvessel density (MVD) could be assessed with immunohistochemistry for endothelial marker ERG in 29 on-treatment tumor samples (10 MPR, 19 NPR) and was significantly higher in MPR samples when compared to non-MPR samples (P = 0.001)." (PMID 34937871, 2021). "Furthermore, we evaluated the expression of the ERG gene based on the CRC proteome profile in the Clinical Proteomic Tumor Analysis Consortium (CPTAC) and found a significantly higher expression level in tumor samples than in normal samples." (PMID 34917613, 2021). "Therefore, with regard to tumor formation, ERG expression has a similar role in RWPE1 xenografts and transgenic mouse models." (PMID 34314419, 2021). "This analysis demonstrated that the association of high JUP expression with adverse tumor features was driven by the subset of ERG‐negative cases." (PMID 33533127, 2021). "In addition, we show that the bromodomain histone reader ZMYND11 is a SPOP substrate implicated downstream of SPOP in the opposing regulation of the ERG and AR pathway in the two tumor subtypes." (PMID 33531470, 2021). "Remarkably, ERG-fused human tumor tissues also displayed the highest SPOP mRNAs levels." (PMID 33531470, 2021). "Second, the tumor biological relevant role of SFRP4 may be abrogated after ERG activation, for example, if ERG target genes become expressed that interfere with SFRP4 function." (PMID 32677026, 2020). "This may be due to there are other factors that exist in the tumor microenvironment to modulate the expression of ERG." (PMID 33425737, 2020). "Subset analyses in 3776 cancers with and 4722 cancers without TMPRSS2:ERG fusion revealed that associations with tumor phenotype and patient outcome were largely driven by the subset of ERG negative tumors." (PMID 32143573, 2020). "We revealed tumor suppressive abilities of miR-223-5p in PCa by negatively targeting ERG gene." (PMID 32489464, 2020). "Other frequent chromosomal alterations include deletions of the PTEN tumor suppressor and other loci including chromosomes 3p, 5q, 8p, 12p, 12q, 13q, 17p, and 18q, most of which are linked to either ERG fusion positive or ERG negative cancers." (PMID 33195694, 2020). "Using the TMPRSS2:ERG fusion as a putative early driver of tumorigenesis, based on its expression in all right-sided tumor foci (B2, B3, R2, and R3), we modeled that the IDC-P and invasive foci identified in the RP descended from IDC-P and invasive foci sampled on biopsy." (PMID 32054861, 2020). "The previous study of neoadjuvant ADT plus abiraterone and enzalutamide also concluded that no tumor with both ERG positivity and PTEN loss responded to the point of MRD7." (PMID 32054861, 2020).